ASTE1 (asteroid structure-specific endonuclease 1)
Description:
Structure-specific DNA endonuclease that specifically cleaves single-stranded DNA and 3' overhang DNA. Contributes to the control of DNA double-strand break repair choice by antagonizing BRCA1-dependent homologous recombination (HR) and promoting non-homologous end-joining (NHEJ). Recruited to the single-stranded DNA ends by SHLD2 and cleaves the 3' exposed DNA ends, therefore inhibiting DNA end resection (necessary for HR) and promoting DNA end protection (necessary for NHEJ).
Synonyms: HT001
Tractability: PROTAC: ubiquitination databases record sites on it.
Gene: Protein-coding gene on chromosome 3 (131,013,066 to 131,027,649, reverse strand). Ensembl gene ENSG00000034533.
Subcellular location (Human Protein Atlas): Endoplasmic reticulum
Gene Ontology:
Molecular function: 3' overhang single-stranded DNA endodeoxyribonuclease activity; protein binding; single-stranded DNA endodeoxyribonuclease activity; DNA endonuclease activity; nuclease activity
Biological process: double-strand break repair via homologous recombination; double-strand break repair via nonhomologous end joining; DNA recombination
Genetic constraint (gnomAD): Loss-of-function variants: 49 observed, 48.17 expected, observed/expected ratio (o/e) 1.02, 90% interval 0.81 to 1.29. The upper end of that interval is the gene's LOEUF score, 1.29, which puts it in group 5 of 6, group 1 being the genes least tolerant of losing a copy. Missense variants: 659 observed, 787.75 expected, observed/expected ratio (o/e) 0.84, 90% interval 0.78 to 0.89. Synonymous variants: 273 observed, 301.37 expected, observed/expected ratio (o/e) 0.91, 90% interval 0.82 to 1.
Homologues: Orthologues: chimpanzee ASTE1 (99% identical), macaque ASTE1 (96% identical), dog ASTE1 (89% identical), rabbit ASTE1 (86% identical), guinea pig ASTE1 (83% identical), pig ASTE1 (80% identical), mouse Aste1 (78% identical), rat Aste1 (77% identical), tropical clawed frog aste1 (48% identical), zebrafish ASTE1 (38% identical), Drosophila melanogaster ast (26% identical).
Diseases named in the same sentence as ASTE1 in open-access papers:
ASTE1 is named in the same sentence as 8 diseases in open-access papers, as found by Europe PMC text mining. Sharing a sentence is not in itself a finding about the gene and the disease. The quoted sentences say what the papers report.
colorectal cancer (3 papers, 2013 to 2017). A primary or metastatic malignant neoplasm that affects the colon or rectum. "No primary disease-associated mutations have been reported for ASTE1; however, secondary mutations in ASTE1 were detected in colorectal cancers with microsatellite instability." (PMID 29104234, 2017). "We also know that ASTE1 has been found mutated in 80% of the colorectal cancers presenting frameshift mutations, and ASTE1 frameshift mutations could play a key role in malignant transformation." (PMID 23344038, 2013). "The ATP2C1/ASTE1 partial overlap (arrowheads) could represent a human-specific regulatory mechanism; when ASTE1 is mutated (e.g., in human colorectal cancers) the SPCA1 protein could accumulate, potentially leading to secretory pathway abnormalities and eventually neoplastic transformation." (PMID 23344038, 2013). "These include ACVR2 (activin receptor type 2), TAF1B (TATA box binding protein-associated factor) and HT001, also known as ASTE1 (asteroid homolog 1), which show mutation rates of more than 80% in MSI-H colorectal cancer." (PMID 25816162, 2015). "When ASTE1 is down-regulated or mutated (e.g., in 80% of colorectal cancers), it no longer prevents the formation of the ATP2C1 isoforms-b, c and d, which are less sensitive to miRNA-mediated inhibition." (PMID 23344038, 2013). "Interestingly, we noted that human ATP2C1a (which doesn’t overlap with ASTE1) has a high number of target sites for miRNAs which are differentially expressed in colorectal cancers, cervical cancers and normal colorectal cells." (PMID 23344038, 2013).
colon cancers (1 paper, 2013). "Additionally, ASTE1 or its protein product Asteorid1 may provide an alternative/complementary diagnostic indicator for SPCA1-induced tumors in skin, breast and colon cancers—the main investigated SPCA1-related tumors." (PMID 23344038, 2013).
fibromatosis (1 paper, 2017). A poorly circumscribed neoplasm arising from the soft tissues. "Our results provide initial evidence for ASTE1 c.230T>C (p.Val77Ala) as a candidate susceptibility variant for DD and LD and a potential role for the ASTE1 gene in the etiology of fibromatosis." (PMID 29104234, 2017). "Since all four family members affected with fibromatosis were double heterozygotes for the LMNA mutation c.736C>T (p.Gln246Stop) and ASTE1 c.230T>C (p.Val77Ala), it is possible that both Lamin A/C haploinsufficiency and an ASTE1 defect are required for disease." (PMID 29104234, 2017).
plantar fibromatosis (1 paper, 2017). A superficial fibromatosis arising from soft tissue of the plantar regions. "With a possible role in epidermal growth factor receptor signaling, ASTE1 may contribute to the increased risk for palmar/plantar fibromatosis in patients with Lamin A/C haploinsufficiency." (PMID 29104234, 2017). "With the possible role of ASTE1 in EGFR signaling, the complex pathway with significant roles in cell–cell communication, cell fate, and proliferation, our findings raise the possibility that ASTE1 c.230T>C (p.Val77Ala) may result in susceptibility to palmar and plantar fibromatosis in our family." (PMID 29104234, 2017).
tumour (4 papers, 2015 to 2022). "Undercoverage of several genes (ACVR2A, ASTE1, KIAA2018, SLC22A9, and TGFBR2) were common events across multiple tumor types, including STAD." (PMID 30281678, 2018). "ACVR2A, TGFBR2, KIAA2018, ASTE1 and SLC22A9 frequently harbour MSI events in STAD and COAD, whereas several other genes are mostly specific to a single tumour type." (PMID 28585546, 2017). "The most recurrent frameshift MSI events are found in ACVR2A (51.6% of the tumours), KIAA2018 (51%), SLC22A9 (50%), ASTE1 (45%), TGFBR2 (44%), NDUFC2 (36%), LTN1 (36%) and SEC31A (36%)." (PMID 28585546, 2017).
cancer (3 papers, 2013 to 2023). A tumor composed of atypical neoplastic, often pleomorphic cells that invade other tissues. "Research suggests that mutations in ASTE1 are induced by the Epstein–Barr virus in gastric mucosal cells, leading to the autonomous expression of CXCL9 by cancer cells through the NF-κB pathway, increasing IFN-γ in the microenvironment and stimulating immune response." (PMID 37664112, 2023).
ASTE1 also shares sentences with these, for which no sentence is quoted: cardiomyopathy (1 paper); Lynch syndrome (1).